CD4 (CD4 molecule)
Diseases named in the same sentence as CD4 in open-access papers (continued):
Sharing a sentence is not in itself a finding about the gene and the disease.
sarcoidosis (continued). "There was a direct correlation between CD4+ and CD8+ in PCPF patients (p < 0.001; r = 0.90), while in IPF and sarcoidosis patients, CD4+ and CD8+ were inversely correlated (p < 0.001 = −0.87 and p = 0.042; r = −0.6, respectively)." (PMID 38540243, 2024). "In sarcoidosis, CD4+ T cells are thought to play a central role in the disease, being driven by specific antigens and HLA-subtypes that are just beginning to be uncovered." (PMID 38353578, 2024). "For example, CD103+CD4+ T-cells in BALF of sarcoidosis patients are lower than in other ILD, while some chemokines able to recruit T-helper lymphocytes, such as CXCL9, CXCL10, and CXCL11, are increased." (PMID 39062076, 2024). "Taken together, we conclude that in PB of treatment-naïve patients with sarcoidosis CD4+ Tm and Tregs displayed an aberrantly activated phenotype, compared with HCs." (PMID 38715030, 2024). "In sarcoidosis, moderate lavage-fluid lymphocytosis (20%–50%) is found in 80% of cases, and the CD4/CD8 T-cell ratio is higher than 3.5 in 50% of cases." (PMID 37250639, 2023). "The contribution and regulation of various CD4+ T cell lineages that occur with remitting vs progressive courses in sarcoidosis are poorly understood." (PMID 36893197, 2023). "Sarcoidosis is a granulomatous interstitial lung disease involving a complex interplay among different cluster of differentiation 4 (CD4+) thymus cell (T-cell) subsets." (PMID 37520566, 2023). "Bearing in mind that the most abundant immune cell type both in peripheral blood and in BALF is T lymphocytes, and sarcoidosis is mostly driven by T cell mechanisms, we investigated adhesion molecules’ expression on T cell subpopulations CD4+ and CD8+." (PMID 37239108, 2023). "When comparing B and Tfh cell counts in patients with sarcoidosis, it was found that the level of B cells and CD4 + CXCR5+ T cells was significantly higher in lymph node biopsy compared to BALF and peripheral blood sample." (PMID 38179278, 2023). "This assumption is confirmed by clinical observations pointing to increased levels of peripheral blood CCR4 + CD4+ cells in sarcoidosis, as well as elevated concentrations of CCL17 chemokines both in the blood serum and at the site of granuloma formation." (PMID 38179278, 2023). "An analysis of female sarcoidosis patients revealed a significant reduction in pSTAT3 and IL-17A levels and a concomitant increase in TGF-β1 levels in CD4+ T cells compared to male sarcoidosis patients." (PMID 36899902, 2023). "Sarcoidosis patients had a higher proportion of lymphocytes and a higher ratio of CD4+/CD8+ cells in their BALF compared with IPF patients." (PMID 37520566, 2023). "Correlation matrix of inflammatory markers in plasma, Treg suppressive function, number of Tregs within the CD4+ subset, and Ki-67+ expression in the sarcoidosis cohort." (PMID 38173720, 2023). "Specifically, we observed a higher abundance of transient memory CD4 T cells in sarcoidosis and a higher abundance of effector memory CD4 T cells in IPF." (PMID 36949950, 2023). "It is well established that the lung lymphocytosis in sarcoidosis patients is attributed to a CD4 T-lymphocyte expansion." (PMID 37161980, 2023). "The exact pathogenesis of sarcoidosis remains incompletely understood, but a cluster of differentiation 4 (CD4+) T-cell-induced immune response is generally acknowledged to be a key player in the maintenance of the granulomatous inflammation." (PMID 37520566, 2023). "Sarcoidosis is a systemic granulomatous disease characterized by the hyperactivation of CD4 T cells, CD8 T cells, and macrophages." (PMID 37223203, 2023). "Coordination between antigen-presenting dendritic cells (DCs) and naïve CD4+ T-cells is important for the formation of granuloma in sarcoidosis." (PMID 40729186, 2023).
sarcoidosis (continued). "Ultimately, muscle biopsy revealed non-caseating granulomatous myositis with perivascular inflammation, extensive muscle fibrosis, and fatty replacement of the muscle with a CD4+ T cell predominant, lymphohistiocytic infiltrate consistent with sarcoidosis." (PMID 37072782, 2023). "Only in an appropriate clinical setting does a CD4/CD8 ratio >3.5 provide a likely diagnosis of sarcoidosis with a specificity of 94%." (PMID 37959363, 2023). "CD4+ T cells from female sarcoidosis patients expressed significantly higher free TGF-b1 than males and the healthy female controls." (PMID 36899902, 2023). "Work from our group identified elevated CD4+ PD1+ T lymphocytes in the peripheral blood of TAK than in healthy controls or sarcoidosis and increased PD1+ Th17 lymphocytes in TAK than in healthy controls." (PMID 37256147, 2023). "CD4+ regulatory T cells show reduced numbers and function in sarcoidosis, confirming that Treg lymphocytes play a role in the altered immune response of this disease." (PMID 37761266, 2023). "Sarcoidosis-like granulomas showed the presence of Langhans and foreign body multinucleated giant cells, CD4 T cells, and a heregeneus collection of MHC II positive and arnase 1 expressing macrophages." (PMID 37109576, 2023). "Recent advances in better understanding the function of diverse immune cells in sarcoidosis suggest, besides CD4+ T cells, a critical role of effector and regulatory T-cell subgroups in the pathogenesis of this disorder." (PMID 37520566, 2023). "We noted similarly increased mRNA and protein expression of the master transcription factor regulating IL-17A production, RORC, in CD4+ T cells from the male compared to the female sarcoidosis patients." (PMID 36899902, 2023). "The proportion of Tregs in patients with active sarcoidosis was higher than in those with inactive sarcoidosis (7.95% ± 1.5% vs. 5.55% ± 0.4% of CD4+ T cells; p = 0.001)." (PMID 37520566, 2023). "BALF examination is avaluable tool in diagnosing sarcoidosis, as many patients exhibit elevatedlymphocytosis and an increased CD4/CD8 ratio in BALF." (PMID 38152007, 2023). "To optimize the BRITE sarcoidosis study flow sorting procedures, we performed iterative optimization experiments to achieve a comparable resolution of the targeted CD4+ T cell subsets across the clinical sites." (PMID 36893197, 2023). "Ki-67, a marker of recent cell division, was upregulated in sarcoidosis PBMCs, in CD4+ and CD8+ T cells, and most substantially in Tregs, suggesting ongoing clonal activation of T cells with compensatory division of Tregs." (PMID 38173720, 2023). "Systemic sarcoidosis diagnosis is supported by a CD4/CD8 ratio > 3.5 and lymphocytosis > 15% in bronchoalveolar lavage (BAL) fluid." (PMID 37721575, 2023). "Tregs, Th1, Th17, and Th17.1 cells constituted 5.7% ± 0.7%, 4.0% ± 0.6%, 12.7% ± 2.6%, and 27.7% ± 3.1% of CD4+ T cells in the BALF of sarcoidosis patients, respectively." (PMID 37520566, 2023). "We observed higher IL-17A mRNA and protein expression in CD4+ T cells from male compared to female sarcoidosis patients." (PMID 36899902, 2023). "Although highly sensitive and specific for sarcoidosis, the CD4/CD8 ratio in the vitreous fluid, can rarely be performed in everyday clinics." (PMID 37721575, 2023). "We have also demonstrated a role for the Th17 CD4+ T cell lineage and related Th17.1 cells in driving sarcoidosis disease progression." (PMID 36893197, 2023). "Consistent with the murine model of lung fibrosis, we observed higher levels of STAT3 mRNA and pSTAT3 protein in CD4+ T cells from the male compared to the female sarcoidosis patients." (PMID 36899902, 2023). "Still, in spite of significant between-study variability, pooled estimates point to lower CD4/CD8 ratios in HP when compared with sarcoidosis and a high ratio (>3.5–4) is currently considered highly specific and useful to support the latter." (PMID 36836922, 2023).
sarcoidosis (continued). "The role of macrophages and CD4+ T cell subtypes has been shown in the immunological profiling of sarcoidosis." (PMID 36824606, 2023). "BAL differential cell counts and BAL lymphocyte phenotypes showed that BALlymphocyte %, BAL T cell %, and BAL CD4/CD8 ratio were statisticallysignificantly higher in the sarcoidosis group." (PMID 38152007, 2023). "In fact, Drake’s group, in 2013, showed that sarcoidosis results in decreased production of IL-2 and INFγ, resulting in reduced CD4+ T lymphocyte activity." (PMID 37761266, 2023). "Next, we found that the relative numbers of CD4+ T cells decreased in patients with sarcoidosis vs. in the control group (40.56% (32.72; 46.24) vs. 48.18% (42.85; 51.70) with p < 0.01)." (PMID 37189479, 2023). "The BALF findings were consistent with sarcoidosis (macrophage: 71%; lymphocytes: 28%; neutrophils: 1.0%; eosinophils: 0%; basophils: 0%; and a CD4:CD8 ratio of 6.34)." (PMID 40729186, 2023). "Among T cells, we found increased levels of IL-2R+ TIGIT+ LAG3+ CD4+ T cells in IPF, increased levels of CXCR3+ CD226+ CD4+ T cells in sarcoidosis, and increased levels of PD1+ TIGIT+ CD57+ CD8+ T cells in CTD-ILDs." (PMID 36949950, 2023). "CD4+ T cell-derived IFN-γ is identified as a central cytokine mediator of macrophage activation in sarcoidosis." (PMID 35668129, 2022). "A distinctive feature of sarcoidosis is that CD4+ T cells interact with antigen-presenting cells to initiate the formation and maintenance of granulomas." (PMID 35371020, 2022). "Sarcoidosis patients show lower CD103 expression on BAL CD4+ cells than patients with other granulomatous ILDs, suggesting that these cells are of peripheral origin." (PMID 35629428, 2022). "TIGIT expression was higher in CD4-positive cells of sarcoidosis patients than in the controls, confirming our previous results." (PMID 36613701, 2022). "Some studies suggest that increased PD-1 expression correlates with decreased CD4+ T-cell proliferation and contributes to the pathogenicity of sarcoidosis upon infection." (PMID 35615369, 2022). "Previous publications demonstrated that the upregulation of PD-1 on CD4+ T cells shaped an immunosuppressive environment in sarcoidosis patients and was correlated with disease aggravation in these individuals." (PMID 36544757, 2022). "Our study described, for the first time, increased PD1, TIGIT and CTLA4 expression on CD4 cells of sarcoidosis patients." (PMID 36613701, 2022). "In sarcoidosis patients, Th-reg (CD4+CD25+CD127−) cells are impaired in their ability to suppress granuloma development." (PMID 35629428, 2022). "Clusters 2, 7, and 12 (referred to as “CD4+ SAR-1”) were highly enriched CD4+FOXP3- clusters in the sarcoidosis samples." (PMID 35668129, 2022). "Sarcoidosis is driven by a T-cell mechanism, in particular the accumulation of activated CD4+ T-cells in the lungs, allowing T-cell attachment and transmigration through the endothelium, endorsed by the expression of integrins." (PMID 35629428, 2022). "From queried PBMC subsets, only significantly increased CD14+ monocyte and significantly decreased CD4+ T-cell proportions were noted in sarcoidosis when compared against controls within both cohorts (MWU test p-value <0.05)." (PMID 36311769, 2022). "For example, n-3 PUFAs prevented differentiation and activation of CD4+ T cells, a key component of sarcoidosis." (PMID 35902843, 2022). "The pathogenesis of sarcoidosis is commonly considered mediated by a cellular immune response involving CD4+ T-helper lymphocytes that characteristically compartmentalize in the lungs." (PMID 36010289, 2022). "CD4+CTLA4+ cell percentages were significantly higher in sarcoidosis than in MPA (p = 0.0079) and HC (p = 0.0117), and numerically higher than GPA (p = 0.0482)." (PMID 36613701, 2022). "Bronchoalveolar lavage (BAL) examination, a minimally invasive tool, contributes to the diagnosis of sarcoidosis on the basis of an elevated CD4+/CD8+ T cell ratio." (PMID 35629428, 2022).
sarcoidosis (continued). "The adaptive immune response in sarcoidosis is a predominant CD4 + type 1 helper (CD4 + Th1) response." (PMID 36314034, 2022). "The role of CD4+ T cells in the immunopathogenesis of sarcoidosis is well established, whereas less is known about cytotoxic CD8+ T cells." (PMID 35629428, 2022). "CD4+PD1+ cells were higher in sarcoidosis and GPA than in HC (p = 0.0250 and p = 0.0253, respectively)." (PMID 36613701, 2022). "CD4+FOXP3- cells were the most abundant T cell type in sarcoidosis, accounting for 70.2% of T cells." (PMID 35668129, 2022). "A second population of CD4+FOXP3- cells was also enriched in the sarcoidosis samples (clusters 3, 8, and 4; referred to as “CD4+ SAR-2”)." (PMID 35668129, 2022). "Our study is the first to report a link between the imbalance in circulating, alveolar and lymph node CD8+ and CD8+CD103+ T cells, ThReg, Tfh and ThNaive and the CD103+CD4+/CD4+ T cell ratio in the development of sarcoidosis." (PMID 35629428, 2022). "Bronchoalveolar lavage (BAL) studies have demonstrated increased numbers of activated CD4+ T cells in the lungs of sarcoidosis patients." (PMID 34868074, 2021). "Data from peripheral blood of patients with sarcoidosis showed that expression of PD-1 on CD4+ T cells, which was elevated at the time of exacerbation, improved to the same level as healthy controls after the clinical findings improved." (PMID 34572417, 2021). "These Th cells are important mediators of immune responses and are thought to organize the granulomatous structure, which is in turn highlighted by CD4 T cell lymphopenia in sarcoidosis patients." (PMID 33903979, 2021). "CD103+CD4+ T cells count as well as CD103+CD4+/CD4 in BALF was also found to be relevant for sarcoidosis diagnosis." (PMID 33807303, 2021). "Bronchoalveolar lavage (BAL) is a safe and minimally invasive procedure for the identification of the CD4+ alveolitis in sarcoidosis." (PMID 33807303, 2021). "In the development cohort, the BALF CD4/CD8 ratio was significantly higher in sarcoidosis patients than in the other ILD patients." (PMID 34217348, 2021). "Most of the studies on the role of lymphocytes in the pathogenesis of sarcoidosis concern assessing the ratio of CD4 to CD8 T cells in BALF." (PMID 34943912, 2021). "The oligoclonal expansion of CD4+ T cells and granuloma features support the fundamental assumption that sarcoidosis is antigen driven." (PMID 34926489, 2021). "Key immunopathologic events in sarcoidosis include an influx of CD4+ T cells, the release of inflammatory cytokines, and the formation of epithelioid granulomas at sites of disease." (PMID 34926489, 2021). "An increased expression of interleukin 17A (IL-17A) has been described in patients with sarcoidosis, and IL-17A-positive CD4+ T cells have also been shown to infiltrate sarcoid lung lesions from patients at different stages of disease evolution." (PMID 34440765, 2021). "For example, Crohn’s disease was described to mimic sarcoidosis with some patients presenting lymphocytic alveolitis in BALF with an elevated CD4/CD8 ratio, a highly specific marker of sarcoidosis." (PMID 34502225, 2021). "The role of CD4 + T cells in the immunopathogenesis of sarcoidosis is well established, while less is known about cytolytic CD8+ T cells." (PMID 34943912, 2021). "An established immunologic feature of sarcoidosis is that the accumulated CD4+ T cells which trigger granuloma formation are strongly Th1 polarized." (PMID 34868074, 2021). "A prevalence of CD4+ T cells in BAL is suggestive of sarcoidosis, whilst prevalence of CD8+ cells is suggestive of hypersensitivity pneumonitis." (PMID 33959573, 2021). "CD4+ T-cells correlated with absolute lymphocytes across the UIC-Sarcoidosis cohort (Spearman's rho = 0.8329, p < 0.0001)." (PMID 33718397, 2021). "One of the pathological findings of sarcoidosis is infiltration of CD4+ T cells into the granuloma and infiltration of CD8+ T cells around the granuloma." (PMID 34572417, 2021).
sarcoidosis (continued). "In one study, peripheral CD4+ T-cells from sarcoidosis patients were found to have spontaneous secretion of IL-2 and IFN-γ that exceeded that of healthy controls." (PMID 33036432, 2020). "CD4+ T lymphocytes are thought to play a critical role in sarcoidosis development by recruiting leukocytes, forming granulomas, and interacting with B cells to stimulate antibody production." (PMID 33036432, 2020). "The effectiveness of medications that inhibit CD4+ T-cell function such as corticosteroids and antimalarials show the importance of T helper cells in the pathogenesis of sarcoidosis." (PMID 33036432, 2020). "In contrast to findings in the BAL of sarcoidosis patients where a CD4+ T cell alveolitis (20–60% total cell count) exists, T cell lymphopenia in the peripheral blood is characteristic of the disease." (PMID 32256501, 2020). "The sarcoidosis granuloma is formed by a distinct conglomeration of multinucleated giant cells and epithelioid macrophages surrounded by a rim of CD4+ T cells." (PMID 33329511, 2020). "High percentages of TH17 CD4+ T-cells expressing PD-1 have been observed in the peripheral blood of sarcoidosis patients." (PMID 33036432, 2020). "One of the most active areas of sarcoidosis research is focused on determining the etiologic antigens that drive the recruitment of CD4+ T cells to the lungs of sarcoidosis patients." (PMID 32256501, 2020). "For example, nicotine acts upon NFκB in macrophages to decrease cytokine production and acts to decrease the Th17/T-reg ratio by its effects on CD4+ lymphocytes, leading to evaluation of this compound as a treatment for sarcoidosis." (PMID 33329511, 2020). "In this study, we show that an increased proportion of CD4+ Vα2.3+ T-cells in BALF is highly specific for sarcoidosis." (PMID 32111204, 2020). "In the clinic, the diagnosis of sarcoidosis is supported by a CD4/CD8 ratio >3.5 and lymphocytosis > 15%." (PMID 32760396, 2020). "While the CD4/CD8 ratio is useful for the diagnosis of sarcoidosis, sensitivity and specificity of this biomarker are low." (PMID 32760396, 2020). "Many subsets of T lymphocytes, including CD8+ T-cells and regulatory T-cells, have been shown to be dysfunctional in sarcoidosis, and the predominant CD4+ T helper cell subset in granulomas appears to be a strong indicator of disease phenotype and outcome." (PMID 33036432, 2020). "PD-1 blockade significantly reduced TGFB-1 produced by Th17 CD4+ T cells from sarcoidosis patients and reduced their ability to induce collagen-1 production in a fibroblast cell line." (PMID 32256501, 2020). "Our previous studies showed a significantly higher percentage of CD34 + progenitor cells in the PB in patients with newly diagnosed sarcoidosis compared to the control group and showed a positive correlation with CD4/CD8 ratios." (PMID 33218322, 2020). "One of the defining features of both CBD and sarcoidosis is an infiltration of activated CD4+ T cells in the lung." (PMID 32256501, 2020). "A recent study demonstrated that PD-1 expression was highest on sarcoidosis CD4+ T cells with a Th17 phenotype." (PMID 32256501, 2020). "The observation that CD4+ T-cells play an important role in the development of sarcoidosis has helped distinguish sarcoidosis from other diseases." (PMID 32760396, 2020). "The proportion of Tregs (CD4+CD25+CD127−) in the peripheral blood of patients with active sarcoidosis was significantly lower when compared to patients with stable sarcoidosis and healthy controls." (PMID 32508842, 2020). "Studies in recent years have found that T helper 17 (Th17) cells and regulatory T cells (Tregs), in addition to a T helper 1 (Th1)/T helper 2 (Th2) CD4+ T-cell imbalance, are closely correlated with the occurrence of sarcoidosis." (PMID 32508842, 2020). "The memory CD4+ T-cell population of sarcoidosis patients also contained a significantly increased frequency of CD27− cells indicating chronic antigenic stimulation." (PMID 33036432, 2020).